NQO1 (NAD(P)H quinone dehydrogenase 1)
Diseases named in the same sentence as NQO1 in open-access papers (continued):
Sharing a sentence is not in itself a finding about the gene and the disease.
colorectal cancer (continued). "Therefore, NQO1’s function in aerobic glycolysis and impact on colorectal cancer (CRC) development and progression was investigated." (PMID 39939940, 2025). "As far as the intervention’s ability to reduce colorectal cancer risk by reducing damage to cellular DNA is concerned, those with the GSTM1, NQO1, and GSTT1 variants are more likely to benefit from consuming PHYTOME meat over standard processed red meat products." (PMID 38337709, 2024). "Therefore, the 609C > T polymorphism of the NQO1 gene causes a decrease in the enzymatic activity of this enzyme, which may contribute to the intensification of the carcinogenic effect of the compounds contained in cigarette smoke on the risk for developing colorectal cancer." (PMID 34356648, 2021). "Thus, we sought to determine if HIF-1α expression correlates with NQO1 levels in human colorectal cancers." (PMID 27966538, 2016). "Thus, we investigated the correlation between NQO1 expression levels and clinicopathological features in colorectal cancer patients utilizing publically available data sets." (PMID 27966538, 2016). "There was no measurable interaction between CYP1A1 and NQO1 polymorphisms in relation to colorectal cancer risk." (PMID 20534171, 2010). "The further single-cell analysis also showed higher expression levels of NQO1 in the stromal cells, epithelial, fibroblasts, and endothelial cells in various cancers, particularly bladder urothelial carcinoma, invasive breast carcinoma, colorectal cancer, and glioma." (PMID 37583897, 2023). "A lack of NQO1 protein due to SNP rs1800566 is associated with many cancers, including adenocarcinoma of the gastrointestinal tract, gastric cardiac carcinoma, and esophageal, lung, bladder, and colorectal cancers." (PMID 34437536, 2021). "Sulindac has been shown to be a potent chemo-protective agent against colorectal cancer in both human and animal models, while sulindac sulfide and sulindac and its two metabolites] have been reported to upregulate the expression of carcinogen detoxification enzymes, including NQO1." (PMID 24505400, 2014). "However, the meta-analysis for the NQO1 609C>T polymorphism and colorectal cancer risk was not performed in Asian population in Chao's study." (PMID 22272361, 2012). "Indeed, in the stratification analysis by cancer site in Caucasians and Asians, significantly elevated risk associated with the NQO1 609T allele was only found for colorectal cancer among Caucasians but not in Asians." (PMID 22272361, 2012). "NQO1 mRNA was highly expressed in the epithelial and myofibroblasts cells in invasive breast carcinoma (GSE138536), endothelial and malignant cells in colorectal cancer (GSE146771), astrocyte (AC)-like malignant cells in Glioma (GSE102130)." (PMID 37583897, 2023). "Consistent with this pro-tumorigenic function for NQO1, high NQO1 expression levels correlate with increased HIF-1α expression and poor colorectal cancer patient survival." (PMID 27966538, 2016). "Consistently, high-level expression of NQO1 correlates with an increased expression of HIF-1α and poor survival in colorectal cancer patients." (PMID 27966538, 2016). "Ten human colorectal cancer cell lines and other types of cancer cell lines including HeLa (cervix), A549 (lung), PC3 (prostate) and U87-MG (brain) exhibited similar NQO1-mediated HIF-1α induction in both normoxia and hypoxia." (PMID 27966538, 2016). "For example, they observed a bright red fluorescence in colorectal carcinoma cells (HT-29) and ovarian cancer cells (OVCAR-3) which are proficient in NQO1; however, for non-small cell lung carcinoma cells (H596) deficient in NQO1, there were no signals." (PMID 39120303, 2024). "Additionally, high CD133 mRNA levels in colorectal carcinoma showed positive correlations with high transcript levels of NRF2 and NQO1." (PMID 35155201, 2021).
colorectal cancer (continued). "We used colorectal cancer (CRC) cell lines and surgical specimens to investigate the methylation status of the KEAP1 promoter region as well as expression of Nrf2 and its downstream antioxidative stress genes, NQO-1 and AKR1C1." (PMID 22325485, 2012). "The present findings showed neither an increased risk of colorectal cancer in relation to the composite of CYP1A1 variant allele and NQO1 187Ser alleles nor an interaction between the composite genotypes and smoking." (PMID 20534171, 2010).
non-small cell lung carcinoma (28 papers, 2012 to 2025). A group of at least three distinct histological types of lung cancer, including non-small cell squamous cell carcinoma, adenocarcinoma, and large cell carcinoma. "The significant SNP on NQO1 (rs1800566) has been linked with poor survival rates in patients with non-small cell lung cancer treated with cisplatin (which belongs to the same class of drugs as oxaliplatin)." (PMID 24924344, 2014). "For example, NQO1 causes apoptosis of non-small-cell lung cancer cells, suggesting unconventional roles for NQO1 in some types of cancer cells." (PMID 23874855, 2013). "Polymorphism in NQO1 was associated with drug resistance in non-small cell lung cancer." (PMID 30970615, 2019). "In cisplatin-resistant non-small cell lung cancer, the utilization of the NQO1 substrate, 2-methoxy-6-acetyl-7-methyljuglone, induced ferroptosis and offered a potential avenue to circumvent chemoresistance." (PMID 40275333, 2025). "One of the most commonly mutated genes in non-small-cell lung cancer is nuclear factor erythroid 2-related factor 2 (NRF2), which drives oncogenic progression in this context in part by activating NQO1 transcription, thereby increasing superoxide scavenging." (PMID 37169843, 2023). "NQO1 was also highly expressed in the epithelial cells in non-small cell lung cancer and invasive breast carcinoma." (PMID 37583897, 2023). "Combining NQO1 inhibitors with conventional chemotherapeutics might enhance anti-tumor immune effects in non-small cell lung cancer." (PMID 38689649, 2024). "However, NQO1 protein expression has recently been reported to predict poor prognosis of non-small cell lung cancers." (PMID 26208303, 2015). "Furthermore, other NQO1+ overexpressing cancer cells, such as A549 non-small cell lung cancer cells, showed synergistic lethality with this combination treatment." (PMID 25590809, 2015). "Expression of NQO1 and clinically relevant proteins in non-small cell lung carcinoma patients with and without KRAS mutations." (PMID 25222473, 2014). "We sequenced KRAS and investigated expression of NQO1 and five clinically relevant proteins (DNMT1, DNMT3a, ERK1/2, c-MET, and survivin) in 108 patients with non-small cell lung carcinoma (NSCLC)." (PMID 25222473, 2014). "In the current study, we implemented a tumor spheroid model to determine whether NAD(P)H quinone oxidoreductase-1 (NQO1) was requisite for self-renewal and promotion of the drug-resistant phenotype in non-small cell lung cancer (NSCLC)." (PMID 36980879, 2023). "Furthermore, the negative expression of NRF2 and NQO1 provides a better prognosis for patients with non-small cell lung cancer (NSCLC)." (PMID 35805773, 2022). "Our objective was to sequence KRAS and compare expression of NQO1 as well as a panel of five clinically relevant proteins in 108 non-small cell lung carcinoma (NSCLC), the most common form of LC, patients with and without KRAS mutations." (PMID 25222473, 2014).
Obesity (27 papers, 2012 to 2025). Accumulation of substantial excess body fat. "Pharmacological activation of NADH oxidation by NQO1 through administration of the substrate β-lapachone has been associated with amelioration of obesity along with glucose intolerance, dyslipidemia, and fatty liver." (PMID 37686150, 2023). "The expression of NQO1 mRNA has also been shown to be positively correlated with glucose tolerance, adiposity, and markers of liver dysfunction, indicating a possible association of NQO1 with the metabolic complications of obesity." (PMID 34947831, 2021). "Our findings on NQO1 are in line with the literature; in fact, acting as a superoxide scavenger, NQO1 preserves cells from the oxidative stress and is implicated in protection against obesity and its related comorbidities." (PMID 36386923, 2022). "NQO1 expression is elevated in adipose tissue, is reduced by diet-induced weight loss and may contribute to the physiological consequences of obesity." (PMID 32635401, 2020). "However, it is still unclear whether NQO1 play etiological roles in the pathophysiology of obesity and metabolic complications, or whether increased NQO1 mRNA expression may be caused by obesity." (PMID 34947831, 2021). "RHAMM appears to play a central role in obesity-induced endocrine and metabolic dysfunction, potentially by modulating antioxidant defense via Nqo1." (PMID 41002415, 2025). "By increasing PGC-1α protein stability in a mitochondrial superoxide-activated NAD(P)H quinone dehydrogenase 1 (Nqo1)-dependent manner in WAT, deletion of Parkin stimulates mitobiogenesis and protects mice from obesity-causing high-fat diets." (PMID 37821940, 2023). "Increased serum FFA levels accompanying obesity have been reported to cause an increase in NOX mRNA expression and a decrease in the expression of genes encoding antioxidant enzymes (NQO1, SOD and catalase) in endothelial cells." (PMID 35073378, 2022). "Briefly described, oxidation of NADH/NADPH through the activation of NQO1 has been found to protect against dyslipidemia, glucose intolerance, hypertension, obesity, and metabolic syndrome." (PMID 34947831, 2021). "Altogether, the data indicate that, although NQO1-Tg mice on HFD develop obesity, they remain insulin sensitive while being protected from liver steatosis." (PMID 33298924, 2020). "Together, these findings indicate a role for NQO1 in the aetiology of obesity and T2D." (PMID 34391409, 2021). "In murine models of metabolic syndrome, β-lapachone-induced pharmacological activation of NADH oxidation by NQO1 showed the substantial improvement of metabolic syndrome and related phenotypes, including obesity, fatty liver, dyslipidemia, and glucose intolerance." (PMID 34947831, 2021). "Alternatively, upregulation of NQO1 could be an adaptive physiological response to human obesity and related complications, and may act as a protective therapeutic tool." (PMID 34947831, 2021). "In addition to oxidation-reduction process, NQO1 is related to obesity, hypertension, renal injury, bone metabolism, tumor growth, and other processes." (PMID 30867055, 2019). "Indeed, the binding regions of EP300, CEBPB, and HDAC2 in the promoters of transferrin (TF), insulin-like growth factor binding protein 1 (IGFBP1) and NQO1, whose expression was increased in obesity and was normalized by CR or RSV, overlap." (PMID 26441656, 2015). "The results demonstrated that the mRNA and protein expressions of HO-1 and NQO-1, two indices of anti-oxidant cell response, were remarkably higher in obese reduction than in control and obesity, and significantly higher in obesity than in control (all p<0.0001)." (PMID 22784636, 2012). "Finally, these findings implicate a role of NQO1 in the metabolic complications of obesity." (PMID 40229590, 2025).
Obesity (continued). "CD248, which has been recently linked with insulin metabolism, NAD(P)H quinone dehydrogenase 1 (NQO1) and tenomodulin (TNMD) were downregulated following LIWL, and their expression was also reduced in SAT of individuals with or without obesity of the LATC and OA cohort." (PMID 40229590, 2025). "Therefore, NAFL, but not obesity per se, was accompanied by the increased expression of NFE2L2 targets genes, including NOX4, which encodes a ROS-producing enzyme, and NQO1, SOD2, and CAT, which encode key antioxidant defense enzymes, but these declined with more advanced disease and fibrosis." (PMID 38060313, 2023). "CD248, which has been recently linked with insulin metabolism, NAD(P)H quinone dehydrogenase 1 (NQO1) and tenomodulin (TNMD) were downregulated following LIWL, and expression was reduced in SAT of individuals with or without obesity of the LATC and OA cohorts." (PMID 40229590, 2025). "Moreover, except for NOX4 expression, which trended lower, NFE2L2, NQO1, SOD2, and CAT gene expression declined in patients with obesity (BMI = 47–74) with NASH and fibrosis (NAS = 5–6; fibrosis score = 1–2) to levels evident in patients with obesity with nonsteatotic livers." (PMID 38060313, 2023).
leukemia (25 papers, 1995 to 2025). A malignant (clonal) hematologic disorder, involving hematopoietic stem cells and characterized by the presence of primitive or atypical myeloid or lymphoid cells in the bone marrow and the blood. "Research shows that SFN can restore NQO1 enzyme activity in leukemia cells carrying this polymorphism, which normally results in reduced activity." (PMID 41246347, 2025). "Carrier individuals of the variant allele in NQO1 609C>T (rs1800566) that have a null or reduced activity of the enzyme have increased risk for leukemia." (PMID 30154939, 2018). "NQO1 609C>T single nucleotide polymorphism (SNP) is associated with decreased enzyme activity and an increased susceptibility to develop leukemia and bladder cancer." (PMID 30154939, 2018). "We have found that NQO1 C609T modified risk in pediatrics leukaemia depending on age range and the variant genotype in combinations with other gene polymorphisms, such as Paraoxonase 1 (PON1) gene variant." (PMID 29225689, 2017). "We have found that infant leukaemia with KTM2A-r was strongly associated with NQO1 C609T variant genotypes (OR: 2.93), while PON1L55M polymorphism increased the risk of ALL in children aged ≥13 months (OR: 3.2)." (PMID 29225689, 2017). "The Oncomine database search was performed to examine the association of NQO1 mRNA expression levels across different sub-type leukemia studies using the reported p values and fold-changes." (PMID 27625902, 2015). "An apparent association of reduced NQO1 expression was found among different types of leukemia specimens compared to normal." (PMID 27625902, 2015). "Low NQO1 activity, implied by the presence of NQO1 gene C609T polymorphism, has been shown in therapy-related myeloid neoplasms, benzene exposure associated leukopenias, infant leukemias associated with MLL gene rearrangements and a subset of de novo AML." (PMID 23066397, 2012). "Comparison of paediatric leukaemias with and without ALL-1 rearrangement indicated significant bias in the former for NQO1 genotypes conferring low or no enzymatic activity, suggesting that inactivating NQO1 polymorphism increases the risk for ALL-1-associated leukaemias." (PMID 14970849, 2004). "Thus, it is reasonable to hypothesize that elevated CYP2E1 activity and/or decreased activity of NQO1 predisposes individuals exposed to xenobiotics to a greater risk of leukemia." (PMID 23066397, 2012). "Therapy-related myeloid neoplasms, infant leukemia associated with mixed-lineage leukemia (MLL) gene rearrangements, and a subtype of de novo acute myeloid leukemia, have low NQO1 activity." (PMID 37047003, 2023). "ERAP1 is the protein target of an anti-leukemia drug, tosedostat, and NQO1 is the protein target of an anti-neurodegressive drug, vatiquinone." (PMID 36388766, 2022). "Consistent with the present study, EANT enhanced the mRNA expressions of NFE2L2, CAT, TXN, HMOX1, and NQO1 genes in leukemia cells in response to EANT-induced oxidative stress." (PMID 34573042, 2021). "It has also been found that resveratrol increases both the activity and expression of NAD(P)H: quinone oxidoreductase-1 (NQO1), a carcinogen-detoxifying phase-II enzyme, in human leukemia K562 cells." (PMID 29194365, 2017). "We have investigated NQO1 and PON1 polymorphisms associated with early-age leukaemia considering acquiring genomic aberrations and age at the onset of the disease." (PMID 29225689, 2017). "In the present study, we observed that DS and DS/Cu sharply reduced the protein level of Nrf2 both in vitro and in vivo in leukemia stem-like cells, as well as blocked the expression of Nrf2 target genes such as NQO1, GSR, and HO-1." (PMID 28518151, 2017). "In leukemia K562 cells resveratrol increased NQO1 expression and induced Nrf2/Keap1/ARE binding to NQO1 promoter." (PMID 29194365, 2017). "Several leukemia cell lines are available and can be used as an in vitro cell model to examine the activation of NQO1 expression in NQO1*2 cells." (PMID 27625902, 2015).
leukemia (continued). "In two analyses that compared clinical human tissue samples of normal vs leukemia patients, under-expressed NQO1 was found in human acute lymphoblastic leukemia (ALL) and chronic myelogenous leukemia (CML)." (PMID 27625902, 2015). "In this communication, we examined microarray data from the Oncomine database to investigate the correlation between under-expression of NQO1 and human leukemia." (PMID 27625902, 2015). "Since down regulation of NQO1 mRNA expression correlates with increased susceptibility for developing different types of cancers, we investigated the link between leukemia and the NQO1*2 genotype by mining a web-based microarray dataset, ONCOMINE." (PMID 27625902, 2015). "Diets rich in SFN or its precursor may result in bioavailable amounts that are sufficient to overcome the “CD” threshold required to reactivate NQO1*2 to expression levels comparable to that of the NQO1 genotype for treatment of patients with leukemia." (PMID 27625902, 2015). "Whether NQO1 expression/activity in leukemia cells that carry the labile NQO1*2 genotype can be induced by broccoli-derived phytochemical sulforaphane (SFN) is currently unknown." (PMID 27625902, 2015). "Furthermore, resveratrol increased NQO1 expression and activity in the K562 leukemia cell line, which was associated with resveratrol-induced Nrf2/Keap1 complex disruption, Nrf2 nuclear translocation, and subsequent binding to ARE within the NQO1 promoter." (PMID 39339278, 2024). "Since the NQO1 gene is located on chromosome 16q22.1, some authors have proposed that inversion may be a primary event leading to disruption of this gene, thereby increasing the likelihood of leukemia." (PMID 23066397, 2012). "In human leukemia HL-60 cells and neuroblastoma SH-SY5Y cells, ALA upregulates NQO1 gene transcription." (PMID 24391783, 2013).